ALB (albumin)
Diseases named in the same sentence as ALB in open-access papers (continued):
Sharing a sentence is not in itself a finding about the gene and the disease.
Cirrhosis (continued). "Given the strength of the preclinical data and widespread use of albumin, this was surprising, and as patients with decompensated cirrhosis are frequently hospitalized, the differing results between this and the outpatient ANSWER studies are important." (PMID 35333783, 2022). "Patients with cirrhosis and spontaneous bacterial peritonitis benefit from the administration of albumin to prevent renal impairment and mortality." (PMID 35268297, 2022). "The ANSWER study has demonstrated that long-term administration of human albumin in patients with cirrhosis and ascites reduces the probability of developing ascites and hospital readmissions." (PMID 35973168, 2022). "In univariate analysis, bacterial infection, the etiology of cirrhosis, bilirubin, albumin, INR, sodium, PWR level, ACLF, and MELD score were significant factors for 28-day adverse outcomes." (PMID 35566588, 2022). "Univariate logistic regression analyses revealed that age, WBC, INR, and TB were risk factors for long-term cirrhosis onset, while SMI, albumin and blood sodium served as protective factors." (PMID 36618679, 2022). "It is also an indicator to evaluate the severity and prognosis of cirrhosis, as decreased ALB levels indicate liver function damage." (PMID 36699093, 2022). "Albumin function, determined by cirrhosis-related posttranslational damage, such as albumin oxidation, is more important than albumin concentration in the development of severe HE and mortality in patients with cirrhosis." (PMID 36555935, 2022). "The structural integrity of albumin is vulnerable to systemic inflammation and oxidative stress as occurs in liver fibrosis and cirrhosis." (PMID 34983435, 2022). "Among variables with P < 0.05, serum albumin level was the strongest predictor of CHE in patients with cirrhosis as shown in S3 Table." (PMID 36449492, 2022). "For the management of cirrhosis, continuous human albumin administration has been shown to be effective for achieving long-term survival." (PMID 34070416, 2021). "By contrast, the ANSWER trial (investigating albumin for the treatment of ascites in patients with hepatic cirrhosis) showed weekly albumin infusions to outpatients with ascites reduced the incidence of infection and improved survival." (PMID 34825153, 2021). "There was statistical significance difference in terms of BMI, HBV-DNA, Cirrhosis, TBIL, ALB, PLT, PT/INR, ALT, blood loss, intraoperative transfusion, and the six liver functional reserve models." (PMID 34335942, 2021). "More recently, our laboratory has exploited transcriptomics to profile the effects of human serum albumin on immune cells from patients with AD cirrhosis and ACLF." (PMID 37360898, 2021). "In general, short-term use of albumin in decompensated cirrhosis is mainly aimed at maintaining or improving volemia." (PMID 33892649, 2021). "The data indicated that long-term albumin supplementation to patients with cirrhosis and ascites improved survival, lowered hospitalizations and prevented complications." (PMID 34571946, 2021). "Albumin levels are an important predictor of the prognosis of HCC and cirrhosis; high albumin levels are known to be associated with a better survival rate." (PMID 33278003, 2021). "Other independent factors were low albumin, age, metastatic neoplasia, chronic liver disease (Child-Pugh C cirrhosis excluded)." (PMID 34170844, 2021). "Albumin is applied regularly to improve osmotic pressure for patients with cirrhosis, but there is only little information on further functions of albumin." (PMID 34571946, 2021). "This patient had advanced cirrhosis with a preoperative albumin level of 2.8 g/dL, a preoperative CRP value of 29.7 mg/L, and a FAR of 0.124 g/L, indicating end-stage disease with a low hepatic synthetic capacity." (PMID 33592030, 2021).
Cirrhosis (continued). "Statistical analysis suggested that there were significant associations between the expression of quite a few hub genes and variables such as histological differentiation, satellite lesions, pN, cirrhosis, and serum albumin." (PMID 34337056, 2021). "It is well established that clinical prognostic factors for HCC in cirrhosis include serum bilirubin and albumin levels, clinically-significant portal hypertension, ascites and functional status." (PMID 34697374, 2021). "In a further study, the role of terlipressin as a vasoconstrictor in the treatment of patients with decompensated cirrhosis and hepatorenal syndrome was tested when albumin was administered together with terlipressin for a mean period of seven days." (PMID 34281177, 2021). "These responses are relevant, since recent studies have suggested beneficial albumin-related immunomodulatory and anti-inflammatory effects, detoxification functions, and amelioration of endothelial dysfunction in patients with cirrhosis." (PMID 33270161, 2021). "The liver function indexes of the HCC group such as AST, GGT, TBIL, DBIL, ALB were significantly higher than those in cirrhosis group, hepatitis group and normal control group (P < 0.05)." (PMID 33971914, 2021). "Infusion of HAS effectively supplements functioning albumin molecules, which is of proven benefit for infection control in patients with cirrhosis." (PMID 33925831, 2021). "Albumin infusion was recently investigated in a randomized, multicenter, open-label trial involving 777 patients hospitalized with decompensated cirrhosis." (PMID 34040918, 2021). "In patients with decompensated cirrhosis, albumin reduces systemic inflammation and cardiocirculatory dysfunction, prolongs overall survival when administered long-term, and is a potential disease-modifying treatment." (PMID 33892649, 2021). "Bilirubin and albumin are rarely altered, except for patients with cirrhosis, who also exhibit prolonged prothrombin time, thrombocytopenia, and neutropenia." (PMID 37363330, 2021). "Low serum albumin level is a cardinal feature and prognostic biomarker of decompensated cirrhosis in patients with Child–Pugh cirrhosis scores B and C." (PMID 34575311, 2021). "Further multivariate analysis identified cirrhosis (HR: 4.329; 95% CI [1.252–14.973]), albumin level (HR: 0.173; 95% CI [0.065–0.466]) and creatinine level (HR: 1.205; 95% CI [1.054–1.378]) as factors independently associated with post-treatment mortality." (PMID 33777520, 2021). "In summary, growing evidence support long-term albumin use in patients with decompensated cirrhosis and ascites, showing a potential role in modifying the natural history of the disease, beyond the treatment of ascites or other specific complications." (PMID 34830508, 2021). "In der „Human-albumin-for-the-treatment-of-ascites-in-patients-with-hepatic-cirrhosis“(ANSWER)-Studie führte eine wöchentliche HA-Gabe zur Reduktion von Mortalität und Komplikationen." (PMID 34618163, 2021). "Most responses indicated unrestricted access to the use of albumin in patients with cirrhosis in Austria." (PMID 33270161, 2021). "Question 2 was an open question asking for indications for albumin substitution in patients with cirrhosis." (PMID 33270161, 2021). "Standardized mean differences in the unweighted cohort showed that significant differences were observed in cirrhosis, tumor size, alanine aminotransferase, aspartate aminotransferase, total bilirubin, and albumin." (PMID 33399908, 2021). "In analysis for HCC development, our findings confirmed that age, male gender, cirrhosis, platelet count, FIB-4 and albumin level were associated with HCC development in CHB patients treated with ETV or TDF." (PMID 33446835, 2021). "The model reflects age, platelet count, hepatitis B e antigen positivity, serum albumin and total bilirubin levels, cirrhosis development, and liver stiffness values measured by transient elastography." (PMID 34885000, 2021).
Cirrhosis (continued). "The serum alkaline phosphatase level is slightly elevated in one-third of patients as well as GGT, but the serum bilirubin, serum albumin level, and prothrombin time are normal, except in patients with NAFLD-associated cirrhosis." (PMID 33681089, 2021). "For patients with hepatic fibrosis or cirrhosis, the reduction of effective hepatocytes will lead to a decrease in the level of ALB and II, V, VII, and X coagulation factors synthesized only in hepatocytes." (PMID 34220379, 2021). "Our study showed that RFA, lower liver function (i.e., lower serum albumin, higher bilirubin, and lower ALBI grade), and the presence of cirrhosis or ascites were significantly associated with lower OS rates according to the univariate analysis." (PMID 34749663, 2021). "When cirrhosis developed, significant decrease in albumin and white blood cell counts were observed." (PMID 33777984, 2021). "In chronic hepatitis, cirrhosis, especially liver cancer, albumin decreases while globulin increases." (PMID 34633988, 2021). "In contrast, the “Albumin for the Treatment of Ascites in Patients with Hepatic Cirrhosis” (ANSWER) RCT and the smaller Pilot-PRECIOSA and INFECIR-2 studies have reported various benefits, most crucially for overall patient outcomes." (PMID 34836265, 2021). "Low albumin levels have been reported to predict the long-term prognosis of patients with liver disease, including those with cirrhosis, as a decline in HFR often begins with decreased serum albumin levels." (PMID 33562238, 2021). "It is as safe and effective as total paracentesis with albumin infusion for the treatment of tense ascites in patients with cirrhosis." (PMID 34231046, 2021). "Low serum albumin is a parameter of the Child-Pugh Scoring system for assessing disease severity in decompensated cirrhosis, and an indicator of prognosis." (PMID 33925831, 2021). "In another RCT, the administration of 12 g/day of BCAA for two years improved the event-free survival, serum albumin concentration, and quality of life of patients with decompensated cirrhosis." (PMID 34068295, 2021). "A recent study reported that the functional capacity of albumin in patients with cirrhosis is impaired." (PMID 34198972, 2021). "A randomized placebo-controlled trial Midodrine and albumin for prevention of complications in patients with cirrhosis awaiting liver transplantation." (PMID 34618163, 2021). "All of them showed that terlipressin was comparable to albumin for the prevention of paracentesis-induced circulatory dysfunction in cirrhosis with tense ascites." (PMID 32676484, 2020). "The cardiovascular changes induced by albumin treatment in patients with decompensated cirrhosis have also been recently studied during long-term administration." (PMID 32837825, 2020). "The reduction in serum albumin is currently considered to be an independent predictor of progression to cirrhosis and mortality." (PMID 32915500, 2020). "Albumin administration is recommended to prevent or treat specific complications of decompensated cirrhosis based on its capacity to expand plasma volume." (PMID 32837825, 2020). "Increasing knowledge of the pathophysiological mechanisms of the disease, as well the pleiotropic properties of the molecule, provides the rationale for considering albumin as a multi-target disease-modifying agent in decompensated cirrhosis." (PMID 32837825, 2020). "Logistic regression analysis was used to identify the most significant factors of advanced liver fibrosis/cirrhosis as indicated by a MELD-Albumin score ≥ 11 or an ALBI score > −2.6 in all patients." (PMID 33490119, 2020). "Binomial logistic regression with all three variables (splenic size, platelet count, and albumin levels) or with splenic size and platelet counts alone was also able to accurately predict cirrhosis." (PMID 33052263, 2020).
Cirrhosis (continued). "A linear regression pattern was demonstrated in the analysis of albumin, bilirubin and ammonia in patients with decompensated cirrhosis correlating with QTc and Tpe." (PMID 32050594, 2020). "In our study, we found a linear correlation between QTc and serum albumin, bilirubin and ammonia, with statistical significance, in patients with decompensated cirrhosis compared to the control group of chronic hepatitis." (PMID 32050594, 2020). "In the cirrhosis group, symptomatic treatment included diuretic treatment (n = 18), albumin infusion (n = 11), and catharsis of the gut (n = 7)." (PMID 32537465, 2020). "Around 26.6% had low serum albumin, 6.4% had pre-existing liver disease (cirrhosis, and moderate to severe fatty liver disease)." (PMID 33170847, 2020). "AST and AP were significantly higher, and albumin and thrombocyte count were significantly lower in patients with cirrhosis as expected." (PMID 32066847, 2020). "WD patients with cirrhosis had significantly lower levels of albumin and triglyceride, while PT, INR, and bilirubin level were significantly higher compared to WD patients without cirrhosis (P < 0.05)." (PMID 32624691, 2020). "For example, in cirrhosis, albumin levels are low and this affects the interpretation of severity based on the ACG criteria." (PMID 32123545, 2020). "Patients with cirrhosis had lower levels of albumin (p < 0.01), urea (p < 0.01) and WBC count (p < 0.05) and higher levels of INR (p < 0.001) compared with patients without cirrhosis." (PMID 32615997, 2020). "On univariate analysis, cirrhosis, baseline ALP >ULN, and baseline albumin level were associated with the occurrence of a liver-related outcome." (PMID 31100458, 2020). "A model using a combination of platelet count, albumin, and spleen size was developed to accurately predict cirrhosis in this cohort." (PMID 33052263, 2020). "Higher liver stiffness has been shown to predict HCC in nucleos(t)ide analogue-treated patients, in addition to cirrhosis, old age, male sex, lower platelet count and lower albumin level." (PMID 32481552, 2020). "The effects of BCAA supplementation were evaluated using the model for end-stage liver disease (MELD) score, CP score, serum albumin, serum bilirubin, incidence of cirrhosis-related events, and event-free survival for 24 months." (PMID 32429077, 2020). "Here, univariate analysis identified total bilirubin, albumin and miR-29c-3p to be the most important factors of advanced liver fibrosis/cirrhosis." (PMID 33490119, 2020). "Exogenous albumin has been administered for decades in patients with decompensated cirrhosis in order to expand the plasma blood volume." (PMID 32837825, 2020). "In patients with cirrhosis, the use of albumin prevents circulatory dysfunction after paracentesis, improves the outcomes in patients with refractory ascites, spontaneous bacterial peritonitis (SBP) and hepatorenal syndrome (HRS)." (PMID 32576140, 2020). "In all cases, cirrhosis was classified as Child-Pugh 5 and modified albumin-bilirubin grade 1 or 2a." (PMID 33080748, 2020). "It is reported that GA is not a good indicator for glucose monitoring in patients with cirrhosis combined with hyperglycemia when their ALB level is <30 g/l." (PMID 32352504, 2020). "It is found that the activity of ALB in patients with hepatitis, cirrhosis, and liver cancer is decreased significantly." (PMID 32963562, 2020). "The labs confirming the diagnosis of cirrhosis were ultrasonography, total bilirubin, total serum albumin, and prothrombin time (clotting profile)." (PMID 32983712, 2020). "The purpose of this review is to examine the hemodynamic and systemic effects of albumin administration in patients with decompensated cirrhosis." (PMID 32837825, 2020). "Determinants of advanced liver fibrosis/cirrhosis according to combined MELD-Albumin score ≥ 11 or ALBI score > −2.6." (PMID 33490119, 2020).
Cirrhosis (continued). "In our study, we used the same volume (150 ml) of albumin 5% and found this amount to be effective only in patients with Child A cirrhosis." (PMID 30987597, 2019). "One of the most important substance with lower production in cirrhosis is albumin, which is not only less produced but also dysfunctional." (PMID 31121839, 2019). "Nonetheless, concerns have been raised regarding the use of albumin in decompensated cirrhosis due to its perceived high cost." (PMID 31278624, 2019). "Intravenous albumin is commonly used to regulate blood volume in patients with decompensated cirrhosis, and has been proven to prevent renal failure." (PMID 30873165, 2019). "The albumin–bilirubin (ALBI) score was originally established to stratify prognosis in patients with cirrhosis." (PMID 31115300, 2019). "Supplementation of albumin in patients with cirrhosis can bind to inflammatory cytokines and acts to protect the blood-brain barrier." (PMID 31596729, 2019). "The ALBI score, derived from a regression model of albumin and bilirubin values, has been proposed as an objective grading system to evaluate the functional liver reserve in patients with cirrhosis or HCC." (PMID 31861706, 2019). "The disease-related clinical information presented in the study only consisted of albumin and bilirubin values to evaluate rifampicin-cirrhosis PBPK model." (PMID 31694244, 2019). "Oxidized serum albumin, that is commonly elevated in patients with cirrhosis, was also recently shown to directly trigger an inflammatory response in peripheral blood mononuclear cells." (PMID 30873165, 2019). "Clinical variables including gender, co-morbidity, hepatitis viral status, preoperative hemoglobin, albumin, and cirrhosis were matched between the two groups." (PMID 30867335, 2019). "The presence of dysfunctional albumin in cirrhosis explains the strong positive reaction of sodium elimination after exogenous albumin administration." (PMID 31121839, 2019). "This analysis evaluated the theoretical cost-effectiveness of albumin in the treatment of decompensated cirrhosis requiring LVP, with SBP, or with HRS, across 3 European countries, Germany, Italy, and Spain, from a hospital perspective." (PMID 31278624, 2019). "Patients with compensated cirrhosis primarily had baseline Child-Pugh scores of 5 (86%), with >100 × 109 platelets/L (77%) and >3.5 g/dL albumin (93%)." (PMID 30923816, 2019). "The ALBI grade is defined using the ALBI score, which is calculated based on levels of bilirubin and albumin in the serum and is representative of liver function in cirrhosis patients." (PMID 31430975, 2019). "In Italy, the use of albumin is recommended by national guidelines to treat or prevent severe complications of cirrhosis such as circulatory dysfunction after LVP, renal failure caused by SBP, and treatment of HRS along with vasoconstrictors." (PMID 31278624, 2019). "Serial administrations of NDMA resulted in decreased serum albumin, biochemical abnormalities, increase of total liver collagen, and well-developed fibrosis and early cirrhosis." (PMID 30679730, 2019). "While the use of albumin in the management of cirrhosis complications is currently recommended and widely employed, the effectiveness of albumin to prevent specific disease complications is less clear." (PMID 30700489, 2019). "The Child-Pugh score estimates life expectancy from the severity of cirrhosis whilst considering albumin and bilirubin levels, prothrombin time, ascites and encephalopathy." (PMID 31581237, 2019). "Human albumin (HA) is currently given as treatment in patients with cirrhosis with the intent to counteract the effective hypovolemia based on its capacity to act as a plasma expander." (PMID 31278624, 2019). "The higher pharmacy costs with albumin were offset by the cost savings of reduced medical complication rates, resulting in lower total costs of therapy in cirrhosis patients treated with albumin." (PMID 31278624, 2019).